POU2AF2 (POU class 2 homeobox associating factor 2)
Description:
Transcriptional coactivator of POU2F3. This complex drives the development of tuft cells, a rare chemosensory cells that coordinate immune and neural functions within mucosal epithelial tissues.
Synonyms: C11orf53; MGC50104; OCA-T1; OCAT1
Tractability: No criterion of Open Targets' tractability assessment is met for any kind of drug.
Gene: Protein-coding gene on chromosome 11 (111,245,725 to 111,286,401, forward strand). Ensembl gene ENSG00000150750.
Subcellular location: Cytoplasm, cytosol; Nucleus
Subcellular location (Human Protein Atlas): Nucleoplasm; Vesicles
Gene Ontology:
Molecular function: protein binding; sequence-specific DNA binding; transcription coactivator activity; DNA binding; POU domain binding
Biological process: positive regulation of DNA-templated transcription
Cellular component: nucleus; cytosol
Genetic constraint (gnomAD): Loss-of-function variants: 20 observed, 21.28 expected, observed/expected ratio (o/e) 0.94, 90% interval 0.66 to 1.37. The upper end of that interval is the gene's LOEUF score, 1.37, which puts it in group 5 of 6, group 1 being the genes least tolerant of losing a copy. Missense variants: 350 observed, 339.37 expected, observed/expected ratio (o/e) 1.03, 90% interval 0.94 to 1.13. Synonymous variants: 141 observed, 153.39 expected, observed/expected ratio (o/e) 0.92, 90% interval 0.8 to 1.06.
Homologues: Orthologues: chimpanzee POU2AF2 (99% identical), macaque POU2AF2 (97% identical), rat Pou2af2 (85% identical), mouse Pou2af2 (83% identical), pig POU2AF2 (78% identical), dog POU2AF2 (77% identical), rabbit POU2AF2 (77% identical), tropical clawed frog c11orf53 (50% identical).
Diseases named in the same sentence as POU2AF2 in open-access papers:
POU2AF2 is named in the same sentence as 13 diseases in open-access papers, as found by Europe PMC text mining. Sharing a sentence is not in itself a finding about the gene and the disease. The quoted sentences say what the papers report.
small cell lung carcinoma (7 papers, 2022 to 2026). Small cell lung cancer (SCLC) is a highly aggressive malignant neoplasm, accounting for 10-15% of lung cancer cases, characterized byrapid growth, and early metastasis. "POU2AF2 (previously known as C11orf53) is a protein-coding gene that acts as coactivator of the POU2F3 that regulates tuft cells in small cell lung cancer and colorectal cancer." (PMID 40506516, 2025). "Our genome-wide CRISPR screen further demonstrates that POU2AF2 depletion or SWI/SNF inhibition leads to a PTEN-dependent cell growth defect, highlighting a potential role of POU2AF2-SWI/SNF axis in small cell lung cancer (SCLC) pathogenesis." (PMID 38453939, 2024). "Additionally, it has also been shown that depletion of POU2AF2/C11orf53 using an in vivo xenograft model of small cell lung cancer repressed tumour growth and delayed progression of disease in mice, showing the tumorigenic potential of this gene in specific cellular contexts." (PMID 41505098, 2026).
colorectal cancer (6 papers, 2016 to 2026). A primary or metastatic malignant neoplasm that affects the colon or rectum. "Common genetic variation at 11q23.1 is associated with colorectal cancer (CRC) risk, exerting local expression quantitative trait locus (cis-eQTL) effects on POU2AF2, COLCA1 and POU2AF3 genes." (PMID 39609081, 2025). "This is the case of the colorectal cancer-associated SNP rs3087967, located in the 3′UTR of the gene POU2AF2/C11orf53, known to have a tumorigenic potential, and for which the mechanistic association to colorectal cancer development has not yet been understood." (PMID 41505098, 2026).
colon cancer (2 papers, 2010 to 2026). "Additionally, we found that a colon cancer-associated SNP in the POU2AF2/C11orf53 3'UTR creates an ectopic DplUSE site, increasing gene expression in zebrafish gut cells and in a human cell line." (PMID 41505098, 2026).
colonic cancer (2 papers, 2010 to 2026). "We found an oncogene containing an SNP associated with human diseases in the DplUSE sequence, which has been associated with an increased risk of development of malignant tumour of colon (MTC) (rs3087967; POU2AF2/C11orf53)." (PMID 41505098, 2026).
infertile (1 paper, 2025). "Pou2af3-/- but not Pou2af2-/- males were also infertile, further decoupling the function of these genes across tissues." (PMID 39609081, 2025).
lung carcinoma (1 paper, 2025). "Our analysis of published ChIPseq data from lung cancer cell lines showed that both POU2AF2 and POU2AF3 are capable of regulating the expression of trans-eQTL targets." (PMID 39609081, 2025).
tumour (3 papers, 2017 to 2026). "Similarly, ApcMin/+Pou2af2-/- mice exhibited significantly larger polyps in the colon than ApcMin/+ mice (FDR=1.24e-5), further supporting Pou2af2 to be associated with increased tumour initiation and progression on this background." (PMID 39609081, 2025). "POU2AF2 is the primary transcriptional activator of tuft cells with a tumour suppressive role in mouse models." (PMID 39609081, 2025). "To interrogate the tumour suppressive effects of Pou2af2 and Pou2af3 expression independently, we crossed single-knockout colonies onto the multiple intestinal neoplasia, ApcMin/+ model and allowed mice to age until they exhibited a moribund phenotype." (PMID 39609081, 2025).
cancer (1 paper, 2023). A tumor composed of atypical neoplastic, often pleomorphic cells that invade other tissues. "Although data are lacking to support a direct interaction between POU2F3 and SOX9 in normal tuft cells, a recent SCLC (i.e., cancer) study reported the direct binding of POU2F3 (and its cofactor, POU2AF2) to the SOX9 gene locus in tuft cell-like SCLC cell lines." (PMID 37179317, 2023).
POU2AF2 also shares sentences with these, for which no sentence is quoted: clear cell renal cell carcinoma (1 paper); Hepatitis (1); leukemia (1); ovarian carcinoma (1); rectal cancer (1).